PVT1 (Pvt1 oncogene)
Diseases named in the same sentence as PVT1 in open-access papers (continued):
Sharing a sentence is not in itself a finding about the gene and the disease.
thyroid cancer (25 papers, 2017 to 2026). "The levels of the lncRNA plasmacytoma variant translocation 1 (PVT1) are significantly increased in thyroid cancer (TC) tissues compared to neighboring normal tissues." (PMID 27802187, 2017). "Based on these results and on the observation that MALAT1 exhibited the higher expression in tumors and that HOTAIR and PVT1 the higher increase as compared to the contra-lateral tissue, we selected MALAT1, HOTAIR, and PVT1 as potential new diagnostic markers for thyroid cancer." (PMID 33030666, 2021). "The association between PVT1 and thyroid cancer remains to be studied further." (PMID 32596158, 2020). "For example plasmacytoma variant translocation 1 (PVT1), which can affect the proliferation of thyroid cancer by regulating the abundance of the thyroid-stimulating hormone receptor." (PMID 40597438, 2025). "Results showed that the PVT1 expression was higher in thyroid cancer, and PVT1 silencing decelerated cell growth." (PMID 35368894, 2022). "Given the important role of both Tg and PVT1 in thyroid cancer, the effect of the rs10283166 SNP on PVT1 expression should be further investigated." (PMID 35216288, 2022). "Previous studies have shown that by forming a complex with EZH2, PVT1 promoted cell proliferation and inhibited apoptosis in liver cancer and thyroid cancer cells." (PMID 34564701, 2021). "In a previous study, PVT1 was reported to promote the proliferation of thyroid carcinoma cells by recruiting EZH2 and mediating TSHR expression." (PMID 32596158, 2020). "Expression of lncRNA PVT1 in thyroid cancer tissues and cell lines (IHH-4, FTC-133, and 8505C) was analyzed using RT-polymerase chain reaction (PCR) and western blotting analysis." (PMID 31336999, 2019). "The effects of lncRNA PVT1 expression on thyroid cancer cell proliferation and cell cycle were analyzed using flow cytometry." (PMID 31336999, 2019). "PVT1 modulated thyroid cancer cell proliferation by recruiting EZH2 and regulating thyroid-stimulating hormone receptor." (PMID 29046366, 2017). "The PVT1 expression was significantly upregulated in 18 types of cancers; although, the PVT1 expression of thyroid carcinoma was significantly lower than that of normal tissues." (PMID 29088881, 2017). "lncRNA PVT1 was reportedto modulate thyroid cancer cell proliferation by recruiting EZH2." (PMID 33650817, 2021). "The authors finally proposed that PVT1 may contribute to pathogenesis of thyroid cancer through EZH2 recruitment and TSHR expression regulation." (PMID 32760219, 2020). "They indicated that the suppression of PVT1 causes cell cycle arrest at G0/G1 phase and significantly decreases cyclin D1 expression, thyroid stimulating hormone receptor (TSHR) expression, and the proliferation of thyroid cancer cells in ATC cell line." (PMID 32760219, 2020). "This study suggested that lncRNA PVT1 may contribute to tumorigenesis of thyroid cancer through recruiting EZH2 and regulating TSHR expression." (PMID 31336999, 2019). "We defined a predictive algorithm based on naïve Bayes classifier for identifying patients with thyroid cancer with accuracy of 94.12% (sensitivity 100% and specificity 91.67%) using MALAT1, HOTAIR, and PVT1 expression in FNA samples and the cytological class." (PMID 33030666, 2021). "Three gene fusions, previously reported only in nonthyroid malignancies (BRAF-TRIM24, SLC12A7-TERT, PVT1-MYC), were described for the first time in thyroid carcinoma." (PMID 41492106, 2026).
lymph node metastasis (24 papers, 2015 to 2023). "In summary, for the first time, using R-Scope ISH in a large TMA, we validated that PVT1 upregulation in GAC (compared to in normal tissues) was associated with lymph node metastases and poor prognosis." (PMID 33076512, 2020). "Results showed that the risk of lymph node metastasis and distant metastasis in high PVT1 expression group was 2.83 and 3.60 folds than those with low PVT1 expression group, respectively." (PMID 30083911, 2019). "High expression of PVT1 was associated with poor differentiation, lymph node metastases, and shorter survival." (PMID 31601234, 2019). "In addition, we also evaluated the association between PVT1 expression and lymph node metastasis, tumor size or distant metastases." (PMID 29348896, 2017). "In the present study, we identify a long noncoding RNA (lncRNA), termed PVT1, which is highly expressed in CSCs and correlated closely with lymph node metastasis of head and neck squamous cell carcinoma (HNSCC)." (PMID 36894542, 2023). "The expression level of PVT1 in patients with lymph node metastasis and tumor infiltration presented with significantly higher expression level of PVT1 than their counterparts without these aggressive disease features." (PMID 32596158, 2020). "In Uygur GC patients, PVT1 expression levels were related to lymph node metastasis and clinical staging (P < 0.05)." (PMID 30679629, 2019). "Patients with ESCC who had increased PVT1 expression also had higher rates of advanced stage and lymph node metastasis, whereas increased CCAT1 expression was only linked to advanced stage and wasn’t associated with lymph node metastasis." (PMID 36624401, 2023). "In Uygur GC, both PVT1 and c-myc were correlated with lymph node metastasis and clinical staging." (PMID 30679629, 2019). "Univariate survival analysis showed that lymph node metastasis, histological grade, TNM stage and high PVT1 expression were prognostic factors." (PMID 33067424, 2020). "Multivariate Cox regression analysis demonstrated that only lymph node metastasis, TNM stage, and high PVT1 expression were independent prognostic factors for GBC patients." (PMID 33067424, 2020). "The results showed that high expression of PVT1 predicted low overall survival rate of OS patients and positively correlated with tumor size, TNM stage lymph node metastasis, and distant metastasis." (PMID 32021563, 2020). "Our findings indicated that the increased PVT1 expression not only predicted poor prognosis of cancer patients, but also positively correlated with tumor size, TNM stage, lymph node metastasis, and distant metastases." (PMID 29348896, 2017). "As extensive data concerning regional lymph node metastasis remains unclear (273 unsure node status and only 17 cases with positive lymph node metastasis), this may compromise the results of correlation between PVT1 expression and regional lymph node metastasis." (PMID 29156724, 2017). "It was observed that serum PVT1 level is mostly increased in CC patients and correlated with tumor size, FIGO stage and lymph node metastasis, demonstrating that PVT1 may be a novel noninvasive biomarker for early diagnosis of CC." (PMID 33371204, 2020). "But sex, age, tumor size, and lymph node metastasis were no obvious correlation with the relative expression levels of PVT1 and miR-194-5p." (PMID 33188158, 2020). "It was demonstrated that high expression of PVT1 was related with lymph node metastasis, histological grade, and TNM stage but not gender, age, and tumor size of GBC patients." (PMID 33067424, 2020). "Higher PVT1 expression level was observed in tissues with lymph node metastasis than tissues without lymph node metastasis." (PMID 28404954, 2017). "Moreover, the negative effect of PVT1 overexpression on predicting high incidence of lymph node metastasis was shown in studies with > 100 patients (pooled OR = 2.93, 95% CI: 1.85–4.66)." (PMID 29348896, 2017).
lymph node metastasis (continued). "The combination of HOTTIP, PVT1, and UCA1 is identified to be a clinical predictive panel to differentiate CRC patients with lymph node metastasis from CRC patients with non-metastatic lymph nodes and healthy people." (PMID 31480503, 2019).
melanoma (23 papers, 2017 to 2026). A malignant, usually aggressive tumor composed of atypical, neoplastic melanocytes. "The role of plasmacytoma variant translocation 1 (PVT1) as a regulator of cell proliferation and metastasis has been studied in melanoma." (PMID 30499222, 2019). "We also measured PVT1 expression in the serum of melanoma patients and analyzed its diagnostic values for melanoma." (PMID 28265576, 2017). "In this study we measured the expression of PVT1 in clinical tissues and serum samples and explored the diagnostic value of PVT1 for melanoma and the effects of PVT1 on melanoma cell proliferation, cell cycle, and migration." (PMID 28265576, 2017). "Because there are many alternative transcription variants of PVT1, we first detected the expression of these different PVT1 variants in melanoma tissues and A375 cells." (PMID 28265576, 2017). "Furthermore, the plasmacytoma variant translocation 1 (PVT1) lncRNA was found as enhanced in the serum of melanoma-affected individuals, with its activity corresponding with tumor state as well as serving as an indicator of postoperative disorder dynamics." (PMID 39777348, 2024). "Further analysis with 51 melanoma patients and 47 non-melanoma patients revealed the ability to discriminate patients from controls based on serum PVT1 levels with a sensitivity of 94.12%, depicting the potential diagnostic value of PVT1 in malignant melanoma." (PMID 37629553, 2023). "It has been shown that PVT1 expression is increased in melanoma tissues compared with benign nevi, and its expression can be a potential diagnostic biomarker and therapeutic target for melanoma." (PMID 37325482, 2023). "Finally, serum levels of Plasmacytoma variant translocation 1 (PVT1) were measured in melanoma patients in the study of Chen and colleagues." (PMID 33503876, 2021). "Collectively, our results indicate that PVT1 functions as an oncogene in melanoma and could be a potential diagnostic biomarker and therapeutic target for melanoma." (PMID 28265576, 2017). "To further verify whether serum PVT1 is derived from melanoma tissues, we calculated the association between PVT1 expression in melanoma tissues and melanoma patients' serum." (PMID 28265576, 2017). "In this study, we focused on the expression, functions, and diagnostic values of PVT1 in melanoma." (PMID 28265576, 2017). "PVT1 silencing inhibits proliferation, migration and invasion in melanoma cells, which is manifested by decreased expression of cyclin D, N-cadherin and vimentin oncogenes, and increased expression of E-cadherin." (PMID 37325482, 2023). "Another ncRNA, PVT1 oncogene (PVT1), was also found to be upregulated in melanoma tissues compared to control." (PMID 37629553, 2023). "In terms of molecular regulation, PVT1 promotes the occurrence and metastasis of melanoma by regulating the expression of EZH2 and miR−200c." (PMID 36601121, 2022). "Another lncRNA that represses miR-200 family expression through EZH2-mediated binding to miR-200 promoter is plasmacytoma variant translocation 1 (PVT1), also upregulated in melanoma." (PMID 34638331, 2021). "The ROC analysis showed that the serum PVT1 level can distinguish the melanoma patients and the control group." (PMID 34670194, 2021). "In vitro studies revealed that PVT1 knockdown inhibits proliferation, induces cell cycle arrest at the G0/G1 phase and enhances the apoptotic events in melanoma cell lines." (PMID 33503876, 2021). "Several studies found PVT1 over-expression in melanoma cell lines and in melanoma tissues compared to melanocytes, identifying its role as a poor prognostic factor." (PMID 33503876, 2021). "In melanoma, the area under the receiver operating characteristic curve value of serum PVT1 has reached 0.937, and PVT1 shows a good correlation with cancer cell proliferation and metastasis." (PMID 31497532, 2019).
melanoma (continued). "To confirm the clinical values of serum PVT1 in monitoring melanoma dynamics, we measured serum PVT1 expression in 17 melanoma patients from both preoperational and postoperational blood." (PMID 28265576, 2017). "The 30 melanoma patients are grouped according to TNM stages, and PVT1 expression is significantly higher in later stages melanoma tissues compared with that in early stages melanoma tissues." (PMID 28265576, 2017). "To explore the therapeutic significance of targeting PVT1 in melanoma, we stably knocked down PVT1 in A375 cells using two independent PVT1 specific shRNAs." (PMID 28265576, 2017). "To further confirm the expression pattern of PVT1 in melanoma, we collected 30 malignant melanoma tissues and 20 age and gender-matched skin tissues with melanocytic nevus and measured PVT1 expression by qPCR." (PMID 28265576, 2017). "Functional experiments showed that overexpression of PVT1 promotes melanoma cells proliferation, cell cycle progression, and migration, while depletion of PVT1 significantly inhibits melanoma cells proliferation, cell cycle progression, and migration." (PMID 28265576, 2017). "In conclusion, our results suggested that PVT1 is upregulated in melanoma tissues and in the serum of melanoma patients." (PMID 28265576, 2017). "In our another previous report, we found that PVT1 is up-regulated in melanoma tissues and serum of melanoma patients." (PMID 28935763, 2017). "Mechanistically, PVT1 directly sponges miR-26b, which had been verified as a tumor suppressor in melanoma." (PMID 29244840, 2017). "In another cohort representing melanomagenesis, including 2 normal skins, 2 benign nevi, 2 atypical nevi, 2 melanoma in suit, and 8 melanoma (GSE4587), PVT1 is gradually increased from skins and nevi, through melanoma in suit, to melanoma." (PMID 28265576, 2017). "To explore the biological functions of PVT1 in melanoma, we stably overexpressed PVT1 in A375 cells by transfecting PVT1 expression plasmid." (PMID 28265576, 2017). "Collectively, publicly available PVT1 expression data and our own data all revealed the upregulated expression of PVT1 in melanoma." (PMID 28265576, 2017). "The results showed that serum PVT1 expression is significantly reduced in postoperational melanoma patients." (PMID 28265576, 2017). "For instance, lncRNA PVT1 was found to be differentially expressed in cutaneous melanoma, which revealed that lncRNA PVT1 might promote the tumorigenesis and metastasis of melanoma by binding to EZH2 and regulating miR-200c expression." (PMID 39659781, 2024). "In 2005, researchers analyzed 2 normal skin samples, 2 benign nevi, 2 atypical nevi, 2 melanoma in situ, and 8 melanoma and observed progressive increases in PVT1 levels from normal skin and benign nevi to atypical nevi, melanoma in situ, and malignant melanoma." (PMID 37629553, 2023). "Accumulating studies have shown that lncRNA-PVT1 (named plasmacytoma variant translocation 1) is upregulated in melanoma tissues compared to adjacent normal tissues, and PVT1 levels are significantly higher in the serum of melanoma patients than in healthy individuals." (PMID 36601121, 2022). "This study suggested PVT1 serum detection as a novel biomarker for melanoma early diagnosis and could have clinical relevance in melanoma as either a diagnostic serum biomarker in early stages or as a monitor of disease in advanced disease." (PMID 33503876, 2021). "PVT1 serum expression levels—defined by quantitative reverse transcription polymerase chain reaction (qRT-PCR)—revealed a significant increase in patients with melanoma (higher expression in later stages compared to early ones) compared with control group." (PMID 33503876, 2021). "PVT1 is overexpressed in melanoma samples and correlates with tumor stage." (PMID 30499222, 2019). "Functional experiments demonstrated that PVT1 promotes melanoma cell proliferation and migration." (PMID 28935763, 2017).
melanoma (continued). "Receiver operating characteristic curve analyses revealed that serum PVT1 level could sensitively discriminate melanoma patients from controls." (PMID 28265576, 2017). "Functional assays revealed that PVT1 has oncogenetic roles in melanoma and could be a potential therapeutic target for melanoma." (PMID 28265576, 2017). "Moreover, serum PVT1 level is reduced after melanoma section, and a significant positive correlation was observed between tissues PVT1 expression and serum PVT1 level." (PMID 28265576, 2017). "Collectively, these data suggested that depletion of PVT1 significantly inhibits melanoma cell proliferation, cell cycle progression, and migration, implying that PVT1 could be a potential therapeutic target for melanoma." (PMID 28265576, 2017). "ROC curve analyses revealed that serum PVT1 level could not only accurately discriminate melanoma patients from controls but also discriminate early stage melanoma patients from controls." (PMID 28265576, 2017). "Further studies are needed to include more samples from multiple center cohorts and from other cancers to elucidate whether serum PVT1 is specific to the diagnosis of melanoma." (PMID 28265576, 2017). "Moreover, serum PVT1 expression is significantly higher in later stages melanoma patients compared with that in early stages melanoma patients." (PMID 28265576, 2017). "Collectively, these data showed that serum PVT1 is derived from melanoma tissues and may indicate melanoma dynamics." (PMID 28265576, 2017). "In this study, we detected PVT1 expression in publicly available melanoma data and our own cohort." (PMID 28265576, 2017). "We investigated PVT1 expression in the publicly available melanoma data from Oncomine database." (PMID 28265576, 2017). "We detected PVT1 expression in melanoma tissues in both public database and our own cohort." (PMID 28265576, 2017). "Collectively, these results showed that serum PVT1 could be used as a novel biomarker for melanoma early diagnosis." (PMID 28265576, 2017). "In this study, using gain-of- and loss-of-function experiments we found that overexpression of PVT1 promotes melanoma cells proliferation, cell cycle progression, and migration, while depletion of PVT1 significantly inhibits melanoma cells proliferation, cell cycle progression, and migration." (PMID 28265576, 2017). "Furthermore, we explored the functions of PVT1 in melanoma cell proliferation, cell cycle, and migration." (PMID 28265576, 2017). "PVT1 overexpression promotes melanoma cells proliferation, cell cycle progression, and migration." (PMID 29244840, 2017). "PVT1 may also influence melanoma by regulating MIR200C via EZH2." (PMID 39372928, 2024). "In addition, studies have shown that the expression of lncRNA plasmacytoma variant translocation 1 (PVT1), an intergenic lncRNA diffusing throughout the nucleus and cytoplasm, was significantly upregulated in human melanoma tissues and was associated with poor prognosis." (PMID 31588640, 2020). "However, the cell-type specific functions and clinical significance of PVT1 in melanoma are still unknown." (PMID 28265576, 2017). "Serum PVT1 level could be used as a sensitive and specific biomarker for melanoma early diagnosis." (PMID 28265576, 2017). "Many studies have demonstrated over- or under-expression of particular types of lncRNAs, such as HOXA6, FDG5-AS1, PVT1, and NKILA in patients with melanoma as a result of developments in sequencing methods." (PMID 39777348, 2024). "Thus, lncRNA PVT1 might be a potential target for the treatment of melanoma." (PMID 39659781, 2024). "Other lncRNAs that contribute to gene repression in melanoma through direct interaction with EZH2 are CASC5, FALEC, HEIH, LNMAT1 and PVT1." (PMID 34638331, 2021). "However, the expression, functions, and clinical values of PVT1 in melanoma are still unknown." (PMID 28265576, 2017). "However, the roles and clinical values of PVT1 in melanoma are still unknown." (PMID 28265576, 2017).